IL13 (interleukin 13)
Diseases named in the same sentence as IL13 in open-access papers (continued):
Sharing a sentence is not in itself a finding about the gene and the disease.
mastocytosis (7 papers, 2011 to 2024). A clonal myeloproliferative neoplasm characterized by the proliferation and accumulation of neoplastic mast cells in one or multiple organs or organ systems. "Allergy and helminths induce strongly Th2-skewed responses associated with cytokines such as IL-4, IL-5, and IL-13, with mastocytosis, eosinophilia, and antibody class-switching to produce IgE." (PMID 27980457, 2016). "The observation of a higher expression of TRAF4 related to Th2 inflammation confirms another observation of the role of the IL-13 gene polymorphism in the pathogenesis of mastocytosis and frequent symptoms of food hypersensitivity affecting this group of patients." (PMID 27086366, 2016).
nephrotic syndrome (7 papers, 2010 to 2024). A collection of symptoms that include severe edema, proteinuria, and hypoalbuminemia; it is indicative of renal dysfunction. "GSEA analysis revealed that the FSTL1 high-expression group was mostly concentrated in pathways like primary focal segmental glomerulosclerosis (FSGS), nephrotic syndrome, and IL-4 and IL-13 signaling and neutrophil degranulation." (PMID 38390317, 2024). "Cytokine gene polymorphism including that of IL-4 and IL-13 in nephrotic syndrome of children with an Arab race has not been explored previously." (PMID 33330285, 2020). "A mechanism whereby excess IL-13 might induce nephrotic syndrome is illustrated by changes in podocyte protein trafficking and proteolytic enzyme secretion seen when these cells are incubated with IL-4 or IL-13 in vitro." (PMID 33330285, 2020). "Furthermore, Buffalo/Mna rats were characterized by Th2 polarization and presented a predominant increase in IL4 and IL13 levels, preceding the development of nephrotic syndrome." (PMID 29942802, 2018). "Therefore, IL-13 may drive the onset of the nephrotic syndrome and the increase of serum IgE levels." (PMID 35371097, 2022). "A selective IL13-Th2 profile characterized children with nephrotic syndrome, who also presented upregulation of IL13 (but not IL4) mRNA by CD4+ and CD8+ cells during relapse." (PMID 29942802, 2018).
prurigo nodularis (7 papers, 2020 to 2025). Prurigonodularis (PN) is a skin disease in which hard crusty lumps are formed on the skin that itches intensely. "IL-31, a cytokine associated with itching and the pathophysiology of prurigo nodularis, is crucial in T-helper 2 skin inflammation by promoting the production of IL-4 and IL-13." (PMID 41110231, 2025). "Type 1 helper T cells (Th1), IL-4/IL-13, and Th2 cytokines interferone-γ are assumed to be factors inducing the spongiotic epidermal changes in prurigo nodularis in the course of disease progression." (PMID 33182351, 2020).
respiratory infections (7 papers, 2011 to 2024). "This indicates that there are significant changes within the IL-13 inflammatory pathway in females only during the acute inflammatory response to a peripheral respiratory infection." (PMID 38879567, 2024). "IL-13 is produced rapidly after respiratory infection in normal mice." (PMID 21573182, 2011). "Hence, controlling for respiratory infections or excluding children with wheezy bronchitis did not essentially affect the associations of IL-5, IL-13, CXCL10, IgA, and TGF-β1 in both serum and whey with AS." (PMID 22805009, 2012).
uveitis (7 papers, 2022 to 2024). An inflammatory process affecting a part of or the entire uvea. "Traditionally, pro-inflammatory Th1/Th17 immune responses are hallmark features of uveitis, while a Th2 response characterized by high levels of IL-4, IL-5, and IL-13 is associated with UC." (PMID 37396905, 2023). "In addition, we also saw an upregulation in another anti‐inflammatory mediator IL‐13, which has been previously shown to reduce ocular inflammation in response to LPS44 and as a modulator of inflammation associated with uveitis." (PMID 36644817, 2023). "It is interesting to note that IL-5 and IL-13 were almost undetectable in non-OT uveitis in our study." (PMID 35646978, 2022). "IL-5, IL-10, and IL-13 showed 3-fold or more significant elevations in OT than in non-OT uveitis patients." (PMID 35646978, 2022). "Moreover, expression of IL-5, IL-9, IL-10, IL-13, and PDGF-AA, were significantly increased in the OT group alone, compared with the non-OT uveitis and control groups." (PMID 35646978, 2022).
acne (6 papers, 2014 to 2025). An inflammatory process of the sebaceous glands which is characterized by comedones, nodules, papules and/or pustules on the skin. "We activated IL-13RA1 by IL-13 in the HaCaT cell line, which resulted in the dysregulation of genes associated with hyperkeratinization, further implicating its role in acne development." (PMID 38854033, 2024). "By targeting IL-13, dupilumab may reduce inflammation, restore skin barrier function, and regulate sebocyte activity, offering a novel approach to mitigating acne pathogenesis through modulation of the IL-13-IL13RA1 axis." (PMID 40401196, 2025). "Thus, our data suggests that the IL-13-IL-13RA1 axis significantly influences keratinocyte proliferation and plays a key role in acne pathogenesis." (PMID 38854033, 2024). "Concurrently, treating human HaCaT cells with IL-13 to activate IL-13RA1 signaling resulted in dysregulation of KRT16, KRT17, and FLG expression, which are associated with hyperproliferation-associated phenotypes in acne." (PMID 38854033, 2024). "Interestingly, we found that the senescence pathway, 1L-7 signaling, and IL-13 signaling are activated only in acne and AK, whereas B Cell receptor signaling was activated in HS, PapR, and CD." (PMID 38014119, 2023). "Interestingly, TREM2 macrophages-recruited mast cell, NKT cell, T cell and neutrophils, all capable of secreting IL-13, this connection bridges inflammation and hyperkeratinization processes in acne, indicating that inflammation precedes and triggers hyperkeratinization." (PMID 39143467, 2024).
brain tumors (6 papers, 2012 to 2023). "On the other hand, the patients with brain tumors had increased levels of IL-12, IL-2, and IL-13 in their cytokine profile." (PMID 37368708, 2023). "Accordingly, both patients with brain tumors had a CSF cytokine profile with high IL-12, IL-13, and IL-2 concentrations." (PMID 37368708, 2023). "IL-13, a T cell differentiating cytokine, was also detected at higher levels in flank compared with brain tumors." (PMID 32690669, 2020). "Our group has developed a therapeutic platform to target IL13Rα2-positive brain tumors by engineering human cytotoxic T lymphocytes (CTLs) to express the IL13-zetakine chimeric antigen receptor." (PMID 24787244, 2014). "In fact, IL-13 zetakine CTLs have been shown to recognize and eliminate brain tumor stem-like initiating cells." (PMID 22496835, 2012).
Cerebral ischemia (6 papers, 2013 to 2025). Restriction of arterial blood supply to the brain associated with insufficient oxygenation to support the metabolic requirements of the tissue. "Specifically, IL-13 alone has shown anti-inflammatory ability in a mouse model of cerebral ischemia." (PMID 34202937, 2021). "To demonstrate the beneficial effects of IL-13 in the cerebral ischemia, we employed a mouse model of permanent middle cerebral artery occlusion (pMCAo) with subsequent administration of murine recombinant IL-13." (PMID 31372938, 2019). "Importantly, our findings have potential implications in the clinical practice and therefore IL-13 treatment can be considered a novel therapeutic approach for the treatment of cerebral ischemia." (PMID 31372938, 2019). "Therefore, we analyzed whether IL-13 treatment modulates the peripheral immune response after brain ischemia." (PMID 31372938, 2019). "Activation of NF-κB induces the production of pro-inflammatory cytokines (IL-4, IL-10, IL-13, TGF-β) and adhesion molecules (IL-6, IL-1β and ICAM-1), thus intensifying tissue injury in cerebral ischemia-reperfusion." (PMID 40656619, 2025).
cholangitis (6 papers, 2018 to 2025). An acute or chronic inflammatory process affecting the biliary tract. "On the other hand, we previously reported that obese mice exhibit severe cholangitis related to a combined profile of IL-13/IL-15/IL-17 and indeed IL-15 neutralization attenuated the disease." (PMID 32716024, 2020). "The loss of intercellular BEC junctions in Abcb4−/− mice was almost normalized in Abcb4−/−/IL-13−/− mice, which is in line with studies showing the disruption of the tight junction-associated BEC barrier by Th2 signals in cholangitis and biliary atresia." (PMID 32846954, 2020). "Zen research showed that the expression of Th2 cytokines (IL-4, IL-5, and IL-13) and regulatory cytokines (IL-10 and transforming growth factor-β) was upregulated in the lesion tissues of patients with IgG4-related sclerosing pancreatitis and cholangitis." (PMID 38669380, 2024). "Therefore, we investigated whether this pathway is involved in progressive fibrosis after cholangitis by analyzing the expression of IL33, IL13, TGFB1, and COL1A1." (PMID 34858903, 2021). "Therapeutic blockade of IL-15 in obese mice with cholangitis resulted in attenuated histological damage, lower numbers of infiltrating neutrophils and CD8+ T cells and reduced levels of proinflammatory cytokines and chemokines including IL-13, IL-17, C-GSF, CCL2, CCL3 and CXCL10." (PMID 29449577, 2018).
endotoxemia (6 papers, 2009 to 2023). "When macrophages are unable to respond to IL-4 and IL-13 cytokine signals in IL4RαLysMCre mice the hosts succumb to endotoxemia, which can be in part rescued by antibiotic treatment." (PMID 30459767, 2018). "IL-13RA1 mediates translational repression of TNF-α mRNA in LPS-stimulated monocytes and is required for IL-13-mediated protection of mice from lethal endotoxemia." (PMID 20105294, 2010). "↑ Veillonellaceae, endotoxemia, and inflammation (IL-6, TNF-α, IL-2, and IL-13) in cirrhotic patients with HE vs. without HE.↑ Enterobacteriaceae, Alcaligeneceae, and Fusobacteriaceae and ↓ Ruminococcaceae and Lachnospiraceae compared with controls." (PMID 37367929, 2023).
eosinophilic disorders (6 papers, 2009 to 2025). "Therapeutics targeting type 2 inflammation, including IL-4, IL-5, and IL-13, are currently in development to treat eosinophilic diseases." (PMID 29034234, 2017). "The advent of better mouse models and ongoing clinical trials targeting multiple pathways, including IL-13, will help garner a better understanding of eosinophil biology and improve therapeutic strategies for treating eosinophilic disorders in the future." (PMID 29034234, 2017). "Biologics targeting the IL-13 pathway have demonstrated efficacy, particularly in subsets of patients with evidence of eosinophilic disease." (PMID 29034234, 2017). "IL-13 levels are elevated in animal models of eosinophilic inflammation and in the blood and tissue of patients diagnosed with eosinophilic disorders." (PMID 29034234, 2017). "Additionally, IL‐13 protein levels increased in the blood and airway tissue (consisting of bronchial mucosa) of patients with eosinophilic disorders." (PMID 40568744, 2025).
fibrosarcoma (6 papers, 2014 to 2023). A malignant mesenchymal fibroblastic neoplasm affecting the soft tissue and bone. "On the other hand, vNKT cells control MDSC activities (e.g., TGF-β secretion) through the release of IL-13 in models of fibrosarcoma and colon cancer." (PMID 34298791, 2021). "The IL-4 receptor-signaling also induces IL-13 production by vNKT cells, resulting in the repression of tumor immunosurveillance in a model of fibrosarcoma." (PMID 34298791, 2021). "CD4+ type II NKT cells produced more of IL-13 and IL-4 than type I cells, and the NKT cell-dependent IL-13 was necessary for tumor recurrence in a growth-regression-recurrence pattern 15-12RM fibrosarcoma tumor model." (PMID 25389427, 2014). "Th2 cells contribute to fibrosarcoma and lung tumor progression by secreting IL-4, IL-5, IL-10, IL-13, and IL-17 and promoting the recruitment of M2 macrophages and eosinophils via the expression of IL-5 and IL-13." (PMID 37568713, 2023). "This was also reported in murine fibrosarcoma, sarcoma and cutaneous squamous cell carcinoma, which may depend on the balance between eosinophil-delivered IL-13 and overall amounts of TLRs, TNFR and IL-1R signaling." (PMID 35210436, 2022). "In a 15-12RM fibrosarcoma tumor model in which tumors show a growth-regression-recurrence pattern, IL-13 had a key role for downregulation of CTLs, and CD1d−/− mice had decreased IL-13 production and resistance to the recurrence." (PMID 29520281, 2018). "In the 15-12RM fibrosarcoma tumor model, although IL-13 was necessary for downregulation of CTL-mediated tumor immunosurveillance, it could not directly downregulate CTL activity as T cells do not have receptors for IL-13." (PMID 29520281, 2018).
hepatic granuloma (6 papers, 2015 to 2024). A granuloma located in the liver. "The association between hepatic granuloma and fibrosis after S. japonicum infection and other mediators (IL-13 and tissue transglutaminases) has been reported." (PMID 33996977, 2021). "Recently, it has been shown that IL-33 and ST2 are involved in Th2-biased immune responses by triggering on the one hand IL-5 and IL-13 release and on the other hand hepatic granuloma pathology induced by Sj infection." (PMID 31200771, 2019). "IL-33 and its receptor ST2 are involved in Th2-biased immune responses through the release of IL-5 and IL-13 and subsequent hepatic granuloma pathology induced by Sj infection." (PMID 31200771, 2019). "The present research shows that GR-MF derived from periovular granulomas of S. mansoni-infected mice produce IL-5 and eotaxin under TGF-β and IL-13 stimulation, and provides evidence that these molecules are relevant for eosinophil production and maintenance in hepatic granulomas." (PMID 26552582, 2015). "In another IL-13 related study, Pae inhibited IL-13-induced collagen synthesis in the in vitro culture of primary hepatic stellate cells (HSCs), implying that Pae could alleviate the hepatic granulomas and fibrosis via modulating IL-13 signaling pathway in HSCs." (PMID 30804784, 2019). "Even though eosinophils are known cell reservoirs of preformed TGF-β and IL-13, HQL-79 decreased eosinophil presence, whilst increasing the fibrogenic cytokines in S. mansoni-driven hepatic granulomas." (PMID 39173086, 2024). "We found that this sensor influences the formation of hepatic granuloma, altering local chemokine (CCL2, CCL3, and CXCL1) and cytokine (IL-5, IL-10, and IL-13) production, macrophage and neutrophil recruitment into the liver, and also is important for promoting collagen deposition." (PMID 32431709, 2020). "Furthermore, the lack of NLRP6 has been shown to significantly reduce periovular inflammation, collagen deposition in hepatic granulomas and mRNA levels of α-SMA and IL-13." (PMID 32431709, 2020). "Such inverse relationship indicates that, once in place within hepatic granulomas, eosinophils may suppress, rather than secrete TGF-β and IL-13 themselves or further their release by other granuloma cell types." (PMID 39173086, 2024).
infertile (6 papers, 2012 to 2025). "Furthermore, regarding the immune response based on the anti-inflammatory cytokine IL-13 expression, the highest IL-13 expression was found in the T2 treatment group (infertile rats administered with forest honey with a 50% concentration) and the lowest expression was found in the T+ and T− groups." (PMID 37767071, 2022). "When we compared cytokine spectra between both groups of infertile patients, we found that e.g. IL-13, IL-7, IL-17, and MIG are higher in patients without ASA, and IL-8 and MIP-1β are higher in patients with ASA." (PMID 22952917, 2012).
Parkinson disease (6 papers, 2016 to 2026). A progressive degenerative disorder of the central nervous system characterized by loss of dopamine producing neurons in the substantia nigra and the presence of Lewy bodies in the substantia nigra and locus coeruleus. "IL-13 is a critical regulator of allergic response and is associated with Parkinson’s disease and cancer." (PMID 38399441, 2024). "Of interest, IL-13 induces rapid phosphorylation of many important synaptic proteins other than glutamate receptors, such as alpha-synuclein, suggesting the possibility that IL-13 deficiency may also play a role in Parkinson’s disease." (PMID 39071802, 2024). "This suggest that under pathological conditions, such as neuroinflammation when reactive oxygen species are produced, IL-13 and IL-4 can participate to tissue damage and thus to Parkinson’s disease or other neurodegenerative disorders." (PMID 27304970, 2016). "The IL-13 system may have a specific role in the pathogenesis and/or the progression of Parkinson’s disease (PD)." (PMID 27304970, 2016). "Also, IL-10 and IL-13 alterations in brain appear specific to AD, and not Parkinson’s disease (PD) or Dementia with Lewy Bodies, which have separate immunologic signatures, and could prove interesting as future differential biomarkers for these conditions." (PMID 39071802, 2024).
silicosis (6 papers, 2006 to 2024). Silicosis is a respiratory disease caused by breathing in (inhaling) silica dust. "Our data support that some cytokines (IL-4, IL-13 and IL-9) associated with a TH2 response are increased in the plasma of patients with silicosis, while cytokines associated with the TH1 response are practically not altered." (PMID 36675056, 2023). "Patients with asbestosis have elevated expression of IL-10 in their AMs, whereas patients with silicosis showed increased levels of IL-10, IL-4, IL-5, and IL13 in their serum." (PMID 32625201, 2020). "In humans, no clinical trials testing the possible role of IL4 or IL13 in silicosis are known, but some IL4 gene polymorphism studies indicate some susceptibility in CWP." (PMID 36675056, 2023). "Patients with silicosis also had increased levels of IL-4, IL-5 IL-10, and IL-13 in their serum." (PMID 35547729, 2022). "The primarily signals that might induce IL-4 or IL-13 in silicosis have not been identified." (PMID 16396683, 2006). "Treg cytokines (TGF-β and IL-10) and Th2 cytokines (IL-4, IL-5, and IL-13), but not Th1 cytokines (IFN-γ, IL2, and IL-12) and pro-inflammatory cytokines (IL-1β, IL-6, and TNF-α), were found to be increased in the sera of patients with silicosis." (PMID 32625201, 2020).